APOE (apolipoprotein E)
Diseases named in the same sentence as APOE in open-access papers (continued):
Sharing a sentence is not in itself a finding about the gene and the disease.
dementia (continued). "Residing in places with fine PM exceeding EPA standards increased the risks for global cognitive decline and all-cause dementia respectively by 81 and 92%, with stronger adverse effects in APOE ɛ4/4 carriers." (PMID 28140404, 2017). "Our analyses indicated that the presence of an APOE ɛ4 allele and greater lifetime leisure-based physical activity increased the risk for dementia." (PMID 28578665, 2017). "When this study was begun, available estimates of absolute risk of dementia for APOE-e4 carriers were largely based on models developed from relative risks observed in one population and incidence data from another, often from case–control samples." (PMID 28323826, 2017). "The authors suggested that adopting a healthy lifestyle, including increased PA, should be utilized as a major preventive strategy to decrease the risk or postpone the onset of dementia among APOE ε4 allele carriers." (PMID 28230730, 2017). "With its background of crucial mediating factor in neurological and cognitive processes, the APOE ε4 allele is a major genetic risk factor investigated for its association not only with dementia forms, but also with normative cognitive development." (PMID 28106810, 2017). "The extent to which risk and protective factors such as sex, education, and apolipoprotein E ε4 allele (APOE*4) carrier status have different associations with dementia in different ethnocultural groups and geographic regions is also not known." (PMID 28323832, 2017). "These experimental data are consistent with our epidemiologic observation of stronger associations between PM2.5 exposure and increased risks for dementia and global cognitive decline in women homozygous for APOE ɛ4 vs ɛ3." (PMID 28140404, 2017). "Biological factors possibly associated with dementia risk include old age, female sex, and Apolipoprotein E (ApoE) ε4 genotype." (PMID 28086755, 2017). "Carriers of the at-risk FTO-AA allele who are also carriers of an apolipoprotein-E (APOE) ɛ4 allele have a significantly increased risk for AD and dementia." (PMID 28515688, 2017). "Results demonstrated that positive APOE ɛ4 carrier status (OR: 2.15, 95% CI: 1.04, 4.42) and greater lifetime physical activity (OR: 1.14, 95% CI: 1.02, 1.28) increased the risk for dementia." (PMID 28578665, 2017). "Like APOE ɛ4, we have demonstrated that decreased height continues to be a significant risk factor for dementia in oldest age." (PMID 28578665, 2017). "Increased default mode network (DMN) coactivation in APOE ε4 carriers at higher risk of future dementia has been demonstrated decades before any clinical, structural or neurophysiological correlate of neurodegeneration in young healthy adult carriers." (PMID 27297241, 2016). "In an attempt to clarify such discrepancies, our aim in this study was to assess possible associations between polymorphisms in the promoter region of the APOE gene and genotypes of its allele E, and the risk for dementia." (PMID 27193889, 2016). "The association between CHRNA7 polymorphisms and dementia was examined after adjustment for age, sex, APOE ε4 status, and education year." (PMID 27249957, 2016). "Because APOE ε4 and smoking are both well-established common risk factors for dementia and the abundant in vitro evidence suggesting their interactions with α7nAChR, our study takes the interactions into account." (PMID 27249957, 2016). "In the general population, advancing age, several genetic factors, notably apoE ε4 genotype, as well as unhealthy lifestyles have been associated with an increased risk of dementia." (PMID 26740685, 2016). "This aim of this study was to add to this discussion by assessing the possible influence of multiple polymorphisms in the promoter region of the APOE gene and genotypes of its allele E on the risk for dementia." (PMID 27193889, 2016). "Age, depression, and the apolipoprotein E (APOE) ε4 allele are independently associated with the latent dementia phenotype “δ” (for “dementia”)." (PMID 27922822, 2016).
dementia (continued). "A growing body of studies has focused on the APOE ɛ4 effect over the lifespan in healthy individuals at risk for developing dementia." (PMID 27395443, 2016). "The modification effect of APOE ε4 allele on the association between smoking and dementia remains controversial." (PMID 25763939, 2015). "Further research is warranted to clarify the modification effect of APOE ε4 allele on association of smoking with dementia." (PMID 25763939, 2015). "We previously reported the effects of family history of dementia and the APOE ε4 allele on cognitive performance over time with data from the Cache County Study of Memory Health and Aging (CCSMHA)." (PMID 26102276, 2015). "On the other hand, APOE was still associated with PS after excluding persons who later developed dementia." (PMID 26252210, 2015). "Future study is warranted to clarify the modification effect of APOE ε4 allele on association of smoking with dementia." (PMID 25763939, 2015). "High-risk genotype of dementia (apolipoportein E, APOE), individual income status and ethnicity were three factors which have been examined in the literature." (PMID 25087013, 2015). "Despite increased efforts to elucidate the complex relationships between AD, SVD, and apoE genotype, the evidence remains equivocal, posing a challenge for understanding the pathogenic mechanisms underlying aging and dementia." (PMID 26161148, 2015). "The main aims of this study were to describe dementia incidence and the associationbetween APOE ε4 carriers and sociodemographic risk factors with dementiaincidence among older Cubans." (PMID 29213926, 2014). "It is well known that ApoE ε4 is a major genetic risk factor for late onset sporadic AD and has also been investigated for its association not only with dementia but also with normative cognitive development." (PMID 24790992, 2014). "Having at least one APOE-ε4 allele was associated with an OR of dementia probability of 1.89 (95% CI: 1.53, 2.21; P < 0.001) in NHW and 1.30 (95% CI: 0.92, 1.85; P = 0.140) in NHB." (PMID 25328845, 2014). "Systemic inflammation is generally considered a risk factor for dementia, but in studies of ApoE ε4 allele carriers CRP has been inversely correlated with both all-cause dementia and levels of CMV IgG." (PMID 24804776, 2014). "Previously documented racial differences in the APOE-dementia association were also seen in this national sample, but differences in relative magnitude are consistent with similar absolute effects." (PMID 25328845, 2014). "Because the type of ApoE expressed is believed to be an indicator of dementia risk and familial hyperlipemia, many clinical studies have begun to utilize ApoE typing in recent years." (PMID 24454848, 2014). "T2DM is an independent risk factor for AD and other dementias, particularly among individuals with the APOE-ε4 genotype." (PMID 25538616, 2014). "The presence of APOE 4 allele is associated with an increased risk not only for dementia but also for cardiovascular disease." (PMID 25520654, 2014). "Further research is needed to assess the possible interaction of statin use and ApoE genotype on risk of AD or dementia." (PMID 24655568, 2014). "When examining quintiles of the AD-GRS, the AD-GRS excluding APOE showed an approximately dose response association with dementia and memory." (PMID 25328845, 2014). "A meta-analysis showed that APOE ε4 allele appeared to be associated with a higher prevalence of dementia in Parkinson disease." (PMID 24621278, 2014). "With respect to risk factors, MCI is much the same as dementia: age, education, APOE genotype, vascular disease, and diabetes have all been identified." (PMID 25538616, 2014). "In the present study, we examined (A) the association between UACR and cognitive performance in Korean adults and (B) a disease modifying effect of APOE E4, a well-known genetic risk marker of dementia, on this association." (PMID 25530658, 2014).
dementia (continued). "Older age, a family history of dementia and APOE ε4genotype were independent risk factors for incident 10/66 dementia." (PMID 29213926, 2014). "In the DS group, cognitive tests scores measuring signs of dementia and APOE ε4 carrier status were associated with LILV and RILV volume." (PMID 24713364, 2014). "Dementia risk was also increased in elderly patients with diabetes and AD-type pathology, particularly in apolipoprotein E-ɛ4 carriers." (PMID 25187809, 2014). "Among NHB males, the AD-GRS excluding APOE was associated with an OR of 3.60 (95% CI: 1.62, 8.00; P < 0.001) for dementia risk compared to an OR of 1.32 (95% CI: 0.66, 2.66; P = 0.436) among NHB females." (PMID 25328845, 2014). "There are many risk factors for dementia, three of which are constant and unchangeable: a family history of dementia, older age, and apolipoprotein E genotype e4 allele." (PMID 25364724, 2014). "Clinical follow-up of the present cohort is necessary to provide actual risk estimates for dementia associated with the APOE ε4 allele in the SCI and MCI groups." (PMID 24914687, 2014). "And, as in familial and sporadic AD, the presence of the apolipoprotein E ɛ4 allele is associated with greater accumulation of Aβ protein in the brains of adults with DS and greater risk of an earlier age of onset of dementia." (PMID 25478025, 2014). "In the present study we investigated for the first time if ApoE genotypes are associated with BBB dysfunction estimated by cerebrospinal fluid-serum albumin ratio in a cohort of patients with different types of dementia." (PMID 24386372, 2013). "Genetic factors play a role as well; the apolipoprotein E (ApoE) ε4 allele is a risk factor for several types of dementia such as AD; especially when occurring along with depression." (PMID 23496988, 2013). "The present study builds on these findings by demonstrating that a major genetic risk factor for age-related cognitive decline and dementia, APOE-ε4, confers increased odds of premature, accelerated cell aging in currently high-functioning healthy individuals." (PMID 23418430, 2013). "The other factors—theε4 allele of the ApoE gene, physical activity, and healthylifestyle—which were all associated with dementia in younger elderly, werenot associated with dementia in the oldest-old." (PMID 23908850, 2012). "One or more APOE ε4 alleles were present in 50% of individuals with dementia, 46% with CI, and 31% NC (χ2 =1.76, p = 0.41)." (PMID 22551361, 2012). "An extensive meta-analysis identified a correlation between the ApoE ε4 allele and dementia in PD, but other studies have disputed this association." (PMID 22577599, 2012). "There have now been numerous studies linking the APOE gene to cognitive performance and risk for dementia." (PMID 23304508, 2012). "In an admixed population of older Cubans we explored the effects of ethnic identity and genetic admixture on APOE genotype, its association with dementia, and dementia prevalence." (PMID 21435264, 2011). "After weighting back, the association between any APOE e4 allele and dementia, adjusted for age, sex and educational level was naturally similar in the case-control sub-sample, although estimated with less precision (PR 2.54, 95% CI 1.85-3.47)." (PMID 21435264, 2011). "Based on the traditional principles of inheritance, the dosage of the ApoE alleles, divided into ε2, ε3, and ε4, is strongly related to the risk for dementia of the Alzheimer's type at an increasing frequency with the increase of ε4 alleles." (PMID 22114744, 2011). "Overall, we found a strong association between APOE genotype and dementia, with effect sizes very similar to those reported in other settings." (PMID 21435264, 2011). "There has been much interest in the potential role of African ancestry in modifying the effect of the APOE genotype and influencing risk for AD and other dementias." (PMID 21435264, 2011).
dementia (continued). "Apoliprotein E4 (apoE4), an allele of apolipoprotein E, which is involved in lipoprotein processing in cells, increases the risk of developing dementia later in life." (PMID 21146447, 2011). "Apolipoprotein E (APOE) plays a central role in lipid metabolism, and is the only established genetic risk factor for late-onset dementia." (PMID 20576093, 2010). "The Honolulu-Asia Aging Study, a population-based prospective cohort study of Japanese American men examined the independent and combined effects of depression and APOE-4 allele on the risk of dementia and its subtypes." (PMID 21369421, 2010). "Our results are also in line with studies demonstrating that APOE ε4 is an important risk factor for dementia." (PMID 20576093, 2010). "APOE ε4 was also associated with VaD, and the strength of the association between APOE and the main dementia subtypes was similar." (PMID 20576093, 2010). "Stroke and the APOE ε4 allele emerged as being strongly associated with dementia in the USA population." (PMID 20576093, 2010). "APOE-4 is a major risk factor for dementia; however, its association with depression has been inconsistent in studies." (PMID 21369421, 2010). "Data from the first dementia study that is representative of the United States population suggest that stroke, the APOE ε4 allele and their interaction are strongly associated with dementia." (PMID 20576093, 2010). "Evidence from clinical samples and geographically limited population studies suggests that vascular health, diabetes and apolipoprotein ε4 (APOE) are associated with dementia." (PMID 20576093, 2010). "Stroke and APOE ε4 were clearly associated with dementia, and these results changed little by additional adjustment." (PMID 20576093, 2010). "When all subjects were examined together, each unit increase in log-transformed tHcy level corresponded to a fourfold increase in the risk for dementia after adjustments for age, sex, education, diabetes, folate, vitamin B12, and APOE genotype (Model 1)." (PMID 20798752, 2009). "Recent evidence also suggests that the risk of dementia is increased synergistically in APOE *E4 carriers exposed to additional health risks, such as head trauma, high alcohol use, comorbid ischemic cerebrovascular disease, or a previous stroke." (PMID 18620605, 2008). "The present study demonstrates that also in this Norwegian population the APOE ε4 allele is a strong risk factor for dementia, similar to what is seen in other Caucasian populations." (PMID 18416843, 2008). "Individuals with MCI who have the epsilon 4 allele of APOE, the gene for apolipoprotein E, appear to be at increased risk of progressing to dementia." (PMID 16539775, 2006). "Furthermore, using a series of sensitivity analyses in UKB, we tested to what extent the observed APOE association with delirium is driven by underlying dementia." (PMID 41286463, 2026). "Model 1 indicates that APOE ε4 significantly increased dementia risk for both sexes." (PMID 41536502, 2026). "Although previous studies suggest that the APOE genotype may modify the association between diet and dementia or AD, the variability in observed findings limits the ability to draw firm conclusions." (PMID 41406402, 2026). "Higher eGDR is associated with prolonged onset of dementia and delayed brain aging among diabetes-free individuals, and could buffer genetic risk of APOE ɛ4." (PMID 41181882, 2026). "Individuals with APOE ε4 allele had significantly higher risk of dementia in both sexes." (PMID 41536502, 2026). "Mediation analyses indicated that TNFRSF11B, APOE and C7 may partially mediate associations between modifiable risk factors and dementia." (PMID 41555457, 2026). "That is, if the present study’s effect sizes for the APOE e4 association with cognitive function after excluding those with dementia are approximately correct, we shall have made a type 2 statistical error by not being able robustly to demonstrate a ‘phenotype effect’ here." (PMID 41053433, 2026).
dementia (continued). "In addition to the increasing range of brain-imaging-based variables that are available, various ‘omics panels will offer clues to the ways by which APOE variation affects cognitive functioning, including the ‘protein signatures’ of dementia risk." (PMID 41053433, 2026). "However, a significant interaction was observed between sex (women vs. men) and carrying two copies of APOE ε4 allele (vs. zero copy) on the risk of dementia (HR: 1.48, 95% CI: 1.10–2.00, p = 0.0094)." (PMID 41536502, 2026). "APOE-ε4 therefore could contribute to increased risk of delirium and also cause or amplify neuropathological changes linked with dementia." (PMID 41286463, 2026). "Furthermore, we identified a significant joint effect of vascular factors and APOE ε4 allele on dementia risk, with women exhibiting a disproportionately higher relative excess risk from this combination." (PMID 41536502, 2026). "Moreover, the detrimental effect of the APOE ε4 allele was more pronounced, yielding a greater relative hazard ratio for dementia compared to men." (PMID 41536502, 2026). "A notable result is the pronounced sex difference in dementia risk associated with the APOE ε4 allele, with women facing a substantially higher risk in those with two copies of APOE ε4 allele (HR = 4.39, 95% CI: 3.52–5.47) than men (HR = 2.92, 95% CI: 2.20–3.88)." (PMID 41536502, 2026). "Unmeasured confounding between APOE (exposure) and dementia (mediator) or delirium (outcome) could be introduced by residual population stratification or linkage disequilibrium between APOE-ε4 and linked causal genetic variants." (PMID 41286463, 2026). "Secondly, we examined whether sex and APOE status, which are two major risk factors for dementia, modify the relationship between eBMD and incident dementia." (PMID 40668308, 2025). "Targeting either APOE-related pathways or social environments in isolation may be insufficient to reduce dementia risk, particularly among socially disadvantaged populations." (PMID 41264567, 2025). "However, it contrasts with previous research in the UKB, which found that the presence of multimorbidity and disease clusters were more strongly associated with dementia risk in non-APOE-ε4 carriers." (PMID 40425445, 2025). "We examined how APOE alleles interact with social adversity to determine dementia risk." (PMID 41264567, 2025). "Previous studies suggest that APOE-ε4 risk may vary across different ethnic groups, and individuals from lower socioeconomic background are at higher risk for dementia." (PMID 40000321, 2025). "Investigating GBA and APOE variants in ADHD cohorts may provide insights into early biomarkers for dementia risk." (PMID 41477452, 2025). "As expected, APOE ε4 remained strongly associated with dementia risk (HR: 2.05, 95% CI 1.86–2.26)." (PMID 41206104, 2025). "In addition to associations with p-tau217, APOE ε4 carriage and dementia, other factors were associated with dream recall in multivariate analyses." (PMID 41001478, 2025). "Moreover, the interaction between APOE ε4*EAT-Lancet diet in relation to all-cause dementia remained with the Knuppel score and the Hanley-Cook score, and with the Hanley-Cook score in relation to AD." (PMID 40222839, 2025). "Finally, while this study identifies statistically robust gene-environment interactions, it does not establish a causal relationship between social adversity and the modulation of APOE-related dementia risk." (PMID 41264567, 2025). "Exposure to PM2.5 levels exceeding the US Environmental Protection Agency (EPA) annual standard of 12 μg/m3 is linked to an 81% increased risk of cognitive decline and a 92% higher risk of all-cause dementia, with APOE ɛ4 carriers being particularly vulnerable." (PMID 41194168, 2025). "KL-VS heterozygosity may be linked to lower likelihood of classification as aMCI or dementia due to AD, and its association with memory might be specific to the aMCI stage of AD and modulated by APOE ε4 status." (PMID 41163083, 2025).